CHD5 (chromodomain helicase DNA binding protein 5)
Diseases named in the same sentence as CHD5 in open-access papers (continued):
Sharing a sentence is not in itself a finding about the gene and the disease.
bladder tumor (1 paper, 2016). "Methylation-specific PCR (MSP) analysis showed that CHD5 was frequently methylated in RCC, prostate and bladder tumor cell lines, which was negatively correlated with the corresponding expression levels." (PMID 26943038, 2016). "Our semi-quantitative RT-PCR data showed that CHD5 was silenced or downregulated in 7/9 RCC, 2/3 prostate and 1/3 bladder tumor cell lines, but readily detected in most human normal adult tissues including kidney and prostate, as well as immortalized normal cell lines (HEK293 and RHEK-1)." (PMID 26943038, 2016).
brain tumors (1 paper, 2009). "CHD5 maps to a region associated with LOH in epithelial tumors, as well as brain tumors and hematopoietic neoplasms, suggesting that CHD5 is a critical player in many types of cancer." (PMID 19536326, 2009).
colorectal tumors (1 paper, 2016). "miR-211 has also recently been implicated in neoplastic growth of colorectal tumors via regulation of the CHD5 tumor suppressor." (PMID 26862518, 2016).
laryngeal carcinoma (1 paper, 2012). Carcinoma that arises from the laryngeal epithelium. "Recently, it was shown that promoter region of CHD5 was methylated in laryngeal carcinoma cell lines." (PMID 22645613, 2012). "In laryngeal carcinoma cell lines, CHD5 functions as growth and invasion inhibitor." (PMID 22645613, 2012). "Although loss of CHD5 has been shown in laryngeal carcinoma, the association between 1p36 aberrations and CHD5 loss in laryngeal carcinoma has not yet been confirmed." (PMID 22645613, 2012). "Demethylation treatment of laryngeal carcinoma cell line with 5-Aza-dC could restore CHD5 expression." (PMID 22645613, 2012).
leukemia (1 paper, 2014). A malignant (clonal) hematologic disorder, involving hematopoietic stem cells and characterized by the presence of primitive or atypical myeloid or lymphoid cells in the bone marrow and the blood. "We further showed that decreased expression of CHD5 in malignant tissues was significantly associated with hypermethylation of the CHD5 promoter, showing a relationship between methylation and reduced CHD5 expression in leukemia." (PMID 24454811, 2014). "CHD5 promoter hypermethylation may be associated with heterozygous loss of CHD5, mutation of the CHD5 gene and transcriptional repression mediated by other factors in our leukemia samples and cell lines." (PMID 24454811, 2014). "In this study, we found that CHD5 is down-regulated in human leukemia cell lines as well as clinical samples." (PMID 24454811, 2014). "In leukemia cases where the normal CHD5 gene is intact, the reduction in CHD5 expression must be due to another mechanism than the absence of the gene sequence." (PMID 24454811, 2014). "Our findings indicate that repression of CHD5 gene expression in human leukemia is mediated in part by DNA methylation of its promoter." (PMID 24454811, 2014). "In this study, quantitative reverse-transcriptase polymerase chain reaction and western blotting analyses revealed that CHD5 was down-regulated in human leukemia cell lines and samples." (PMID 24454811, 2014). "Treatment with DNA methyltransferase inhibitor 5-aza-2′-deoxycytidine (DAC) activates CHD5 expression in human leukemia cell lines." (PMID 24454811, 2014). "Bisulfite DNA sequencing of the identified regulatory element revealed that the CHD5 promoter was hypermethylated in human leukemia cells and samples." (PMID 24454811, 2014). "The association between these epigenetic aberrations and the putative transcriptional inactivation of CHD5 gene was assessed in leukemia cell lines." (PMID 24454811, 2014). "CHD5 is down-regulated in several cancers, including leukemia and is responsible for tumor generation and progression." (PMID 24454811, 2014). "Our findings indicate that repression of CHD5 gene expression in human leukemia is mediated in part by hypermethylation of the identified CHD5 regulatory element." (PMID 24454811, 2014). "Given the pivotal role of CHD5 in leukemia, we hypothesize that CHD5 is inactivated in leukemia and sought to elucidate the mechanism of inactivation." (PMID 24454811, 2014). "To determine whether CHD5 expression was down-regulated in leukemia, we initially examined expression level of CHD5 mRNA and protein in leukemia cell lines." (PMID 24454811, 2014). "In summary, we have shown that CHD5 is down-regulated in leukemia cells by promoter methylation, which suggests that CHD5 is a potential prognostic biomarker that may enrich therapeutic options." (PMID 24454811, 2014). "To evaluate the contribution of epigenetic silencing to the reduced CHD5 gene expression observed in leukemia cells, we investigated whether the identified CHD5 promoter regulatory element was methylated in leukemia cell lines." (PMID 24454811, 2014). "Additionally, MCs obtained from bone marrow from leukemia patients were analyzed for CHD5 expression." (PMID 24454811, 2014). "Several results support the hypothesis that the methylation of the CHD5 promoter is responsible for the reduced expression observed in leukemia cells." (PMID 24454811, 2014). "However, the mechanism of CHD5 down-regulation in leukemia is largely unknown." (PMID 24454811, 2014). "According to the National Cancer Institute (NCI), the frequency of 1p36 deletion in leukemia samples is less than 5%, and some of these 1p36 deletions do not include the CHD5 gene." (PMID 24454811, 2014). "In addition, reduced CHD5 expression was not accompanied with hypermethylation of the CHD5 promoter in some leukemia samples." (PMID 24454811, 2014).
lymphoma (1 paper, 2014). A malignant (clonal) proliferation of B- lymphocytes or T- lymphocytes which involves the lymph nodes, bone marrow and/or extranodal sites. "Deletions of regions including Chd5 in a mouse model of chromosomally unstable lymphoma showed that CHD5 is one of only three genes mapping to the minimally common region of deletion that they discovered in human T-cell acute lymphoblastic leukemia/lymphoma." (PMID 24454811, 2014).
male infertility (1 paper, 2021). The inability of the male to effect fertilization of an ovum after a specified period of unprotected intercourse. "CHD5 deficiency affects spermatogenesis, resulting in male infertility in mice with phenotypes ranging from sperm deficiency to reduced sperm count." (PMID 33621950, 2021).
mental retardation syndrome X-linked (1 paper, 2019). "In pluripotent stem cells SNF2 helicase family members such as CHD5 (chromodomain helicase DNA binding protein 5) and ATRX (a-thalassaemia/mental retardation syndrome X-linked) have been implicated in the control of class III MERVL and class II IAP elements, respectively." (PMID 30902974, 2019).
metastatic disease (1 paper, 2022). "Analysis of patient cohorts confirmed that low CHD5 expression in NB is associated with stage 4 metastatic disease and decreased survival." (PMID 34789839, 2022).
pancreatic ductal adenocarcinoma (1 paper, 2016). An infiltrating adenocarcinoma that arises from the epithelial cells of the pancreas. "In addition, intriguingly, low-expression of CHD7 was correlated to the survival of gemcitabine treated pancreatic ductal adenocarcinoma patients, suggesting the potential of CHD7 as a tumor suppresser gene like CHD5 in some tumors." (PMID 27955690, 2016).
peritoneal mesothelioma (1 paper, 2020). A benign or malignant mesothelial neoplasm that arises from the peritoneum. "Notably, we found WDPM specific mutations in EHD1, FBXO10, CHD5, MAGED1, ATM, and TP73 genes that were absent in peritoneal mesothelioma." (PMID 32545767, 2020).
prostate carcinoma (1 paper, 2016). A carcinoma that arises from epithelial cells of the prostate gland. "Data from Oncomine database also indicated that CHD5 mRNA expression was frequently decreased in kidney, bladder and prostate cancers compare with their adjacent control tissues." (PMID 26943038, 2016). "Moreover, the data retrieved from cBio database revealed the presence of copy number loss of CHD5 in ccRCC, papillary RCC (TCGA) and prostate cancer." (PMID 26943038, 2016). "CHD5 significantly inhibits clonogenic growth and tumor xenograft growth, thus as a functional tumor suppressor in multiple common cancers, including breast, colon, lung, ovary and prostate cancers, although no report about the expression and function of CHD5 has been reported in RCC yet." (PMID 26943038, 2016).
stomach adenocarcinoma (1 paper, 2022). "CHD5 was frequently mutated in stomach adenocarcinoma (7%) and UCEC (14%), whereas CHD7 mutations were identified in 8% of CRC cases." (PMID 35789070, 2022).
tumor (69 papers, 2008 to 2026). "In mouse models, Chd5 functions functions as a dose-dependent tumor suppressor, as its heterozygous loss induces immortalization and tumorigenesis, while having three copies leads to senescence, apoptosis, and perinatal lethality." (PMID 41278204, 2025). "Among 100 tumor-normal pairs sequenced, somatic mutations of 1p tumor suppressors KIF1Bβ and CHD5 were most frequent (2%) after ALK and ATRX (8%), and BARD1 (3%)." (PMID 35768791, 2022). "Decreased CHD5 expression due to E43Q corresponded to increased colony formation in SK-N-AS cells, suggesting loss of long-term tumor suppressive activity." (PMID 35768791, 2022). "Our first pan-cancer analysis of CHD5 revealed that the gene was lowly expressed in most tumor tissues compared with adjacent normal tissues and that there was an association between CHD5 expression and clinical prognosis." (PMID 35955624, 2022). "Potentially interesting variants such as a missense variant in the G protein-coupled receptor SMO (chr7:128850945 G>A) and an SV affecting a putative tumour suppressor CHD5 (predicted loss of function) were identified." (PMID 30736342, 2019). "Genetic mutations of the tumour-suppressing gene CHD5 have conduced to the understanding of human oncogenesis." (PMID 29907144, 2018). "In contrast, a chromodomain helicase DNA binding 5 (CHD5) gene, which encodes an ATPase-dependent DNA-binding protein with two PHDs, is a tumor suppressor in neuroblastomas." (PMID 28055972, 2017). "CHD5 facilitates expression of a tumor-suppressive network that includes p16 and p19, encoded by the cyclin-dependent kinase inhibitor 2A (Cdkn2a) locus." (PMID 24454811, 2014). "Reactivation of CHD5 expression after induction chemotherapy was observed mainly in those high risk tumors with induced tumor cell differentiation features." (PMID 20950435, 2010). "CHD5 gene and protein expression was reexamined after induction chemotherapy in a subset of high risk tumors to identify potential changes reflecting tumor response." (PMID 20950435, 2010). "We investigated the effects of induction chemotherapy (3 cycles) on CHD5 expression in 12 high risk NB cases with available paired diagnostic and post-chemotherapy tumor specimens for qRT-PCR and immunohistochemical analyses." (PMID 20950435, 2010). "The functional changes reflected the observed clinical phenotypes in both cases, and suggested that these novel 1p36 variants, while deleterious to tumor suppressors such as CHD5, may contribute to gain-of-function in others such as KIF1Bβ." (PMID 35768791, 2022). "Mutations of the H3-binding domains impair the tumor suppressive activity of CHD5." (PMID 35768791, 2022). "Our findings also suggested that CHD5 might be an independent prognostic factor in multiple cancers and that the low expression of CHD5 was associated with poor prognosis in major tumor types." (PMID 35955624, 2022). "When looking at the incidence of mutations in the CHD5 encoding the protein in tumor samples, using TCGA and the web tool cBioPortal for visualization and analysis, we identified a total of 11 mutations in CHD5 mRNA from TCGA dataset, consisting of 8 missense and 3 truncating mutations." (PMID 29568352, 2018). "Although CHD5 is currently recognized as a potential biomarker and key mediator in multiple human malignancies, the potential mechanism underlying its antitumor function related to tumor immunity remain unclear." (PMID 35955624, 2022). "Consistently, heterozygous deletion of the CHD5 gene as well as the promoter CpG island hypermethylation is frequently observed in various human cancers, suggesting that inactivation of CHD5 caused by deletion and epigenetic silencing commits to tumorigenesis and tumor progression." (PMID 24709709, 2013).
tumor (continued). "A single study identified the rs187960998 SNP in mature miR-211 as a tumor suppressor, demonstrating its ability to inhibit CC cell proliferation and invasion through upregulation of CHD5." (PMID 39684686, 2024). "Chromodomain Helicase DNA Binding Protein 5 (CHD5) has demonstrated its unique role as a novel tumor suppressor in a variety of cancers." (PMID 37479876, 2023). "EZH2 was found to regulate the proliferation of HCC cells and promote HCC progression in a variety of ways, for example, previous studies have shown that CHD5 is a tumor suppressor." (PMID 37268997, 2023). "Here, we evaluated the role of CHD5 in tumor immunity in a pan-cancer multi-database using the R language." (PMID 35955624, 2022). "Differences in the expression of CHD5 between the normal and tumor samples in each tumor type were then calculated." (PMID 35955624, 2022). "The findings from our pan-cancer analysis showed that CHD5 was differentially expressed in the tumor tissues as compared to the normal tissues." (PMID 35955624, 2022). "CHD5 is a bona fide tumor suppressor gene in NB, as shown by attenuation of clonogenicity in vitro and decrease of tumorigenicity in mice when overexpressed." (PMID 34789839, 2022). "This is consistent with the notion that the tumor-suppressive effect of CHD5 in NB is confined to cells with 1p deletion." (PMID 34789839, 2022). "Next, we evaluated the differences in the expression of CHD5 in patients with different tumor types." (PMID 35955624, 2022). "Previous studies have found that targeting CDK9 in cancers can inhibit oncogenes (e.g. MYC) and reactivate tumor suppressor genes (e.g. CHD5)." (PMID 35394046, 2022). "In the present study, we first demonstrated that CHD5 was differentially expressed between most cancer tissues and the adjacent normal tissues, which suggested that CHD5 was a potential tumor suppressor gene in most cancers." (PMID 35955624, 2022). "For example, chromosome 1p deletions affect many potential tumor suppressors including CHD5, CAMTA1, KIF1B, CASZ1, UBE4B, and MIR34A." (PMID 35246212, 2022). "Several other putative tumor suppressors in the chromosome 1p or 11q deletion regions including CHD5, UBE4B, CADM1, and ATM, have patterns that are similar to KIF1B, where a subset of samples exhibit strong ASE in the absence of deletions." (PMID 35246212, 2022). "CHD5, a tumor suppressor gene, is under the control of KDM4A, whose silencing restores CHD5 expression by decreasing H3K36me2/me3 histone marks in its locus." (PMID 34778065, 2021). "This 1p36 syntenic deletion, which included the Arid1a and Chd5 tumor suppressors, resulted in increased anchorage independent growth and defects in differentiation." (PMID 34885007, 2021). "Chromodomain helicase DNA binding protein 5 (CHD5) is well known as a tumor suppressor gene involved in multiple tumors." (PMID 34305525, 2021). "The locus contains numerous cancer-associated genes (CASP9, SDHB, and others), including chromodomain helicase DNA binding domain 5 (the CHD5 gene), which was recently identified as a tumor suppressor in vivo." (PMID 34205964, 2021). "CHD5 also functions as one of the tumor suppressor genes in other types of tumors, e.g., gliomas, breast, colon, lung, ovarian, and prostate cancers." (PMID 34616726, 2021). "Previous genetic studies have identified candidate neuroblastoma tumor suppressor genes, including KIF1Bb, CHD5, miR-34a, ARID1A, and CAMTA1 located at 1p36." (PMID 34885007, 2021).